MAGEA6 (MAGE family member A6)
Description:
Activator of ubiquitin ligase activity of RING-type zinc finger-containing E3 ubiquitin-protein ligases that acts as a repressor of autophagy. Proposed to act through recruitment and/or stabilization of the Ubl-conjugating enzyme (E2) at the E3:substrate complex. May play a role in tumor transformation or aspects of tumor progression. In vitro promotes cell viability in melanoma cell lines.
Synonyms: CT1.6; MAGE6; MAGE3B; MAGE-3b
Tractability: PROTAC: UniProt records ubiquitination sites on it; ubiquitination databases record sites on it.
Gene: Protein-coding gene on chromosome X (152,766,136 to 152,769,716, reverse strand). Ensembl gene ENSG00000197172.
Gene Ontology:
Molecular function: protein binding; histone deacetylase binding
Biological process: negative regulation of autophagy; negative regulation of transcription by RNA polymerase II
Cellular component: nucleus
Homologues: Orthologues: zebrafish ndnl2 (20% identical), Drosophila melanogaster MAGE (17% identical). Paralogues in human: MAGEA3 (96% identical), MAGEA12 (84% identical), MAGEA2 (84% identical), MAGEA2B (84% identical), MAGEA4 (68% identical), MAGEA1 (68% identical), MAGEA8 (63% identical), MAGEA11 (60% identical), MAGEA9 (58% identical), MAGEA9B (58% identical), MAGEA10 (52% identical), MAGEB16 (41% identical), and 25 more.
Diseases named in the same sentence as MAGEA6 in open-access papers:
MAGEA6 is named in the same sentence as 38 diseases in open-access papers, as found by Europe PMC text mining. Sharing a sentence is not in itself a finding about the gene and the disease. The quoted sentences say what the papers report.
melanoma (17 papers, 2013 to 2025). A malignant, usually aggressive tumor composed of atypical, neoplastic melanocytes. "MAGEA6 (MAGE family member A6) is a protein coding gene associated with melanoma and osseous dysplasia." (PMID 34885040, 2021). "Contrastingly, in melanoma cells where MAGEA6 and CT-GABRA3 are activated, the promoter is completely demethylated, including at critical CpG sites located near the transcription start sites." (PMID 34462486, 2021). "An intriguing observation was that in the melanoma cell lines where we detected hypomethylation and activation of MAGEA6/CT-GABRA3, the promoter of GABRA3 exhibited marked hypermethylation." (PMID 34462486, 2021). "MAGEA6 and CT-GABRA3 become aberrantly co-activated in a significant proportion of tumors, including melanoma, and our previous studies indicated that this was caused by DNA demethylation of the MAGEA6/CT-GABRA3 promoter." (PMID 34462486, 2021). "MAGE-A proteins, including three of the four genes identified in our analysis (MAGEA2, MAGEA3, and MAGEA6), have recently been implicated in resistance to CTLA-4 ICB in melanoma patients." (PMID 32117236, 2020). "We continued to assess the effect of DAC treatment on the expression of MAGEA1, MAGEA3/MAGEA6, and MAGEA9 in a broad panel consisting of 37 cell lines originating from female reproductive organ tumors, melanoma, hematopoietic, or other cancers." (PMID 40791813, 2025).
breast carcinoma (8 papers, 2011 to 2024). "The expression of MAGEA6 was found to be associated with the poor survival of breast cancer patients." (PMID 34503106, 2021). "None of the primary tumors showed reactivation from the Xi, although in some tumors, MAGEA6 expression was detected from the presumed Xa, similarly to our data in breast cancer cell lines." (PMID 25653311, 2015). "Besides, MAGEA6 serves as hub genes in the chemo-resistance of breast cancer." (PMID 39370446, 2024). "MAGEA6, as a member of the MAGEA family, has been verified to be a hub gene MAGEA6 involved in chemo-resistance and survival prognosis of breast cancer." (PMID 39370446, 2024). "MAGEA2, MAGEA3, MAGEA4, MAGEA6, and MAGEA12 are up-regulated in the CDKN2A alteration group, amongst which MAGEA3 (HR=1.61[1.27-2.04], p=8.2e-5), MAGEA4 (HR=1.38[1.08-1.77], p=0.011), and MAGEA12 (HR=1.65[1.10-2.48], p=0.015) are accompanied by worse prognosis in breast cancer." (PMID 37857018, 2023).
lung carcinoma (8 papers, 2013 to 2025). "For example, MAGEA3 and MAGEA6 are both associated with colorectal and lung cancers, and MAGEA6 and MAGEA11 are coexpressed in prostate cancer." (PMID 34202157, 2021). "MAGEA6 can promote pancreatic, lung cancer and colorectal cancer carcinogenesis by inhibiting autophagy." (PMID 36250008, 2022). "In particular, MAGEA3 and MAGEA6 expression are highly correlated in colon and lung cancer, as is MAGEA6 and MAGEA11 expression in prostate cancer." (PMID 34202157, 2021). "For lung cancer, GMPS, EPHA10, C10orf54, and MAGEA6 are highly expressed in different subtypes; for liver cancer, CMYA5, DEPDC6, FAU, VPS24, RCBTB2, LOC100133469, and SLC35B4 are significantly expressed in different subtypes." (PMID 33747053, 2021). "DDX17 can bind the mRNAs of MYL9 and MAGEA6 to promote the expression of MYL9 and MAGEA6, regulate the process of cytoskeletal reorganization and autophagy in lung cancer cells, thus promoting the proliferation, migration, invasion and tumor growth of lung adenocarcinoma cells." (PMID 41322492, 2025).
glioma (6 papers, 2019 to 2024). A benign or malignant brain and spinal cord tumor that arises from glial cells (astrocytes, oligodendrocytes, ependymal cells). "Recently, we found that melanoma antigen A6 (MAGEA6) silencing restored AMPKα1 expression, causing mTORC1 inhibition and glioma cell apoptosis." (PMID 33159013, 2020). "Our previous study has shown that MAGEA6 sequesters AMPKα1 in glioma cells, causing mTORC1 overactivation and cancer cell growth." (PMID 31727877, 2019). "The results of this study suggest that Lnc-THOR-IGF2BP1 association is important for MAGEA6 expression in glioma cells." (PMID 31727877, 2019). "We have previously shown that MAGEA6 knockdown by targeted short hairpin RNA (shRNA) restored AMPKα1 expression, causing glioma cell death and apoptosis." (PMID 31727877, 2019). "Pan and colleagues reported that MAGEA6 is expressed in human glioma tissues and cells and correlates with AMPKα1 downregulation." (PMID 36139694, 2022). "Further, LncRNA THOR (Lnc-THOR) silencing inhibited glioma cell survival by depleting MAGEA6 and inhibiting mTOR signaling." (PMID 33159013, 2020). "In the present study, we will show that Lnc-THOR-IGF2BP1 cascade is essential for MAGEA6 expression in glioma cells." (PMID 31727877, 2019). "Taken together, Lnc-THOR depletion inhibits human glioma cell survival possibly by activating MAGEA6-AMPK signaling." (PMID 31727877, 2019). "Contrarily, MAGEA6 silencing/depletion restored AMPKα1 expression and induced AMPK activation, causing downstream mTORC1 inactivation and glioma cell death." (PMID 31727877, 2019). "Moreover, MAGEA6 knockdown restored AMPKα1 expression and inhibited glioma cell survival via mTORC1 inactivation as well as glioma xenograft growth, while AMPKα1 silencing ameliorated glioma cell death." (PMID 36139694, 2022). "Moreover, CRISPR/Cas9-induced IGF2BP1 knockout activated MAGEA6-AMPK signaling as well, causing A172 glioma cell apoptosis." (PMID 31727877, 2019). "The regulatory mechanism of MAGEA6 expression in glioma is elusive." (PMID 31727877, 2019). "Therefore, although further studies are needed to explore the detailed underlying mechanisms, here we propose that Lnc-THOR-IGF2BP1 association is vital for MAGEA6 expression and AMPK inactivation in human glioma cells." (PMID 31727877, 2019). "Reversely, MAGEA6 silencing inhibits human glioma cell cells via re-activation of AMPK signaling." (PMID 31727877, 2019). "Importantly, Lnc-THOR shRNA or knockout activated MAGEA6-AMPK signaling in glioma cells." (PMID 31727877, 2019). "The IGF2BP1 knock-out induced by CRISPR/Cas9 also activated MAGEA6-AMPK signaling, leading to the apoptosis of glioma cells (A172)." (PMID 36672345, 2023). "For example, MAGEA6-AMPK signaling is activated by knock-out IGF2BP1 with CRISPR/Cas9, resulting in the apoptosis of glioma cells (A172) and inhibiting the survival of human glioma cells, so as to achieve a therapeutic effect." (PMID 36672345, 2023). "Significantly, Lnc-THOR silencing/KO or IGF2BP1 KO induced MAGEA6 degradation (both mRNA and protein), AMPKα1 protein accumulation, and AMPK activation in A172 glioma cells." (PMID 31727877, 2019). "Inhibition of Lnc-THOR-IGF2BP1 cascade will induce MAGEA6 downregulation, AMPKα1 expression, and AMPK signaling activation, inhibiting glioma cell survival in vitro and in vivo." (PMID 31727877, 2019). "The RIP results show that MAGEA6 mRNA directly binds to the IGF2BP1 protein in A172 cells and the primary glioma cells." (PMID 31727877, 2019). "Lnc-THOR depletion activates MAGEA6-AMPK signaling and inhibits human glioma cell survival." (PMID 31727877, 2019). "Therefore, IGF2BP1 is important for MAGEA6 expression and AMPK inactivation in glioma cells." (PMID 31727877, 2019). "A later study showed that MAGEA6-AMPK signaling was activated by silencing the long non-coding RNA THOR, which inhibited human glioma cell survival." (PMID 36139694, 2022).
bladder cancer (4 papers, 2021 to 2025). "This included strong upregulation of cancer‐testis antigens (MAGEA3, MAGEA6, MAGEA10) and neuroendocrine‐associated genes such as NEB and NELL2, features linked to higher tumour grade, invasion and lineage plasticity in bladder cancer." (PMID 41425537, 2025). "Next, we determined the predicted location and protein–protein interaction of MAGEA3 and MAGEA6 genes in bladder cancer." (PMID 38254738, 2024). "A data analysis of bladder cancer patients further uncovers the possibilities of utilizing MAGEA2, MAGEA3, MAGEA4, MAGEA6, MAGEA10, MAGEA11, and MAGEA12 members as diagnostic biomarkers for bladder cancer." (PMID 38254738, 2024). "Regarding CDKN2A and its interaction with MAGEA6 very little is known so far, moreover previous studies identified higher expression of MAGEA6 in early stage bladder cancer." (PMID 34885040, 2021). "Due to their highly antigenic properties and other diverse roles during cancer progression, the aberrant expression of MAGEA family, especially MAGEA3 and MAGEA6, may serve as prognostic biomarkers for poor outcomes in bladder cancer patients." (PMID 38254738, 2024). "These values suggest that MAGEA3 and MAGEA6 may serve as prognostic biomarkers for bladder cancer patients." (PMID 38254738, 2024). "In summary, using a series of bioinformatics and retrospective analyses, the present study identified a subset of seven genes (CDC20, CDKN2A, CTSV, FOXM1, KRT23, MAGEA6, and S100A9), which were significantly associated with progression and prognosis of bladder cancer." (PMID 34885040, 2021). "MAGEA6 is overexpressed in a variety of human cancers, including bladder carcinoma." (PMID 34885040, 2021). "It was found that frequencies of genomic alterations among MAGEA family members in bladder cancer were MAGEA1 1.8%, MAGEA2 1.6%, MAGEA3 1.9%, MAGEA4 1.6%, MAGEA6 2.6%, MAGEA8 1.7%, MAGEA10 2%, MAGEA11, 2.1%, and MAGEA12 2.4%." (PMID 38254738, 2024). "The expression profile of CDC20, CDKN2A, CTSV, FOXM1, KRT23, MAGEA6, and S100A9 were significantly higher in bladder cancer specimens compared with normal bladder tissue in patients." (PMID 34885040, 2021). "The PPI network analysis of three databases identified the following subsets of DEGs, including CDC20, CDKN2A, CTSV, FOXM1, KRT23, MAGEA6, and S100A9, which were significantly upregulated in bladder cancer." (PMID 34885040, 2021). "Interestingly, MAGEA2, MAGEA3, MAGEA4, MAGEA6, MAGEA10, MAGEA11, and MAGEA12 exhibited significant differences in their expression in bladder cancer compared to normal bladder samples." (PMID 38254738, 2024). "To further understand the association between MAGEA3 and MAGEA6 with S100A9, we explored the OncoDB cancer database, a large-scale multi-omics database, and performed pairwise gene expression correlation analysis between MAGEA3 and MAGEA6 and S100A9 in bladder cancer patients." (PMID 38254738, 2024). "A total of seven genes, including CDKN2A, CDC20, CTSV, FOXM1, MAGEA6, KRT23, and S100A9 were confirmed with strong prognostic values in bladder cancer and validated by qRT-PCR conducted in various human bladder cancer cells representing stage-specific disease progression." (PMID 34885040, 2021).
colorectal cancer (4 papers, 2021 to 2025). A primary or metastatic malignant neoplasm that affects the colon or rectum. "This study investigates the role of MAGEA6 in perineural invasion (PNI) in colorectal cancer (CRC)." (PMID 40145793, 2025).
esophageal cancer (3 papers, 2022 to 2025). A primary or metastatic malignant neoplasm involving the esophagus. "However, MAGEA6 positively regulates MSMO1 and facilities the capacity of migration and invasion in esophageal cancer cells." (PMID 36046654, 2022).
prostate carcinoma (3 papers, 2017 to 2022). A carcinoma that arises from epithelial cells of the prostate gland. "Database search confirmed that MageA11 and MageA6 are co-expressed in human prostate cancer samples." (PMID 28542476, 2017).
hepatocellular carcinoma (2 papers, 2022). A malignant tumor that arises from hepatocytes. "For example, microRNA 448 targets MAGEA6, a negative regulator of AMPK, thereby activating the pathway and suppressing stemness in hepatocellular carcinoma." (PMID 35195687, 2022).
liver cancer (2 papers, 2021). An epithelial or non-epithelial malignant neoplasm that arises from the liver. "Similarly, in 28 cancer cell lines that exhibit p53TC and p53TI signature (that includes cells from liver cancer and other cancer types) had relatively similar levels of C19MC miRNA expression, however, the MAGEA-3, MAGEA-6 and MAGEA-12 mRNAs were selectively upregulated in p53TI subset." (PMID 34135394, 2021).
lung adenocarcinoma (2 papers, 2024 to 2025). A carcinoma that arises from the lung and is characterized by the presence of malignant glandular epithelial cells. "Studies have shown that DDX17 regulates autophagy and actincytoskeleton remodeling in lung adenocarcinoma through MAGEA6 andMYL9 signaling." (PMID 38802460, 2024).
renal cell carcinoma (2 papers, 2017 to 2021). "MAGEA6 silencing was found to inhibit human colorectal and renal cell carcinoma and prevented mTOR signaling." (PMID 34943938, 2021).
triple-negative breast carcinoma (2 papers, 2024). An invasive breast carcinoma which is negative for expression of estrogen receptor (ER), progesterone receptor (PR), and human epidermal growth factor receptor 2 (HER2). "Melanoma-associated antigen A6 (MAGEA6) is well known to have oncogenic activity, but the underlying mechanisms by which it regulates tumor progression and chemo-resistance, especially in triple-negative breast cancer (TNBC), have been unknown." (PMID 39370446, 2024).
atherosclerosis (1 paper, 2022). A disease characterized by the build-up of fatty material and calcium deposition in the arterial wall resulting in partial or complete occlusion of the arterial lumen. "Several risk markers related to the immune response that have key roles in atherosclerosis were identified, including the top aging marker MMP8, disease markers KIR3DL1 and MAGEA6, network markers based on degree (RBM10, PJA2, and CMTM6), and network markers based on betweenness (IRAK1 and VAMP8)." (PMID 35706446, 2022).
COVID-19 (1 paper, 2022). A disease caused by infection with severe acute respiratory syndrome coronavirus 2. "We speculate that the high expression of these immune-related genes can alleviate the aggravation of COVID-19 symptom severity, such as GAGE12F, TNMD, MAGEA6, MAGED2, and XAGE1A." (PMID 36118230, 2022).
metastatic tumor (1 paper, 2015). "In contrast, seven other non-synonymous or frameshift mutations (in genes UGT3A2, PLCG1, OR10K1, COL9A1, MAGEA6, CNBD1 and LG14) were detected only in the metastatic tumor, indicating a selection and proliferative advantage of cells with the diverse genotype under sunitinib treatment." (PMID 26474454, 2015).
multiple myeloma (1 paper, 2013). "This analysis revealed significant down-regulation by CYCLON knockdown of a proliferation gene expression signature that includes cancer testis antigens (e.g. MAGEA1, MAGEA3, MAGEA6, GAGE1), and that characterizes an aggressive subtype of multiple myeloma." (PMID 23828858, 2013).
osteosarcoma (1 paper, 2024). A usually aggressive malignant bone-forming mesenchymal neoplasm, predominantly affecting adolescents and young adults. "IFITM5, MMP13, PANX3, and MAGEA6 were some of the most overexpressed genes in osteosarcoma samples, while SLC4A1, HBA1, HBB, AQP7 genes were some of the top downregulated genes." (PMID 38966281, 2024).
pancreatic ductal adenocarcinoma (1 paper, 2020). An infiltrating adenocarcinoma that arises from the epithelial cells of the pancreas. "Importantly, in pancreatic ductal adenocarcinoma cell models, MAGEA6 suppresses macroautophagy (autophagy)." (PMID 32270762, 2020).
sarcomatoid mesothelioma (1 paper, 2024). A diffuse malignant mesothelioma arising from the pleura and less often the peritoneum. "Conversely, several genes reported to be expressed in sarcomatoid mesothelioma were preferentially expressed in cluster 1: members of the MAGE family MAGEA1, MAGEA3, MAGEB2 and MAGEA6." (PMID 38212075, 2024).
stomach adenocarcinoma (1 paper, 2025). "Our comprehensive analysis reveals that MAGEA3 and MAGEA6 are epithelial-derived genes that are significantly associated with immune infiltration and tumor immune microenvironment remodeling in stomach adenocarcinoma." (PMID 41452900, 2025). "In this study, we systematically explored the role of epithelial-related differentially expressed genes (DEGs), particularly MAGEA3 and MAGEA6, in shaping the tumor immune microenvironment (TME) of stomach adenocarcinoma (STAD)." (PMID 41452900, 2025).